TSC2 (TSC complex subunit 2)
Diseases named in the same sentence as TSC2 in open-access papers (continued):
Sharing a sentence is not in itself a finding about the gene and the disease.
tumor (continued). "In summary, SERPING1 emerges as a novel tumor suppressor gene and SP5/SERPING1/TSC2 is a promising therapeutic target in the context of LUAD." (PMID 39962118, 2025). "This sensitivity is mediated through UL38’s inactivation of the TSC complex subunit 2 (TSC2) protein, a central metabolic regulator that possesses tumor-suppressive properties." (PMID 38117060, 2024). "Consistent with the effects of PRAS40 in tumor cells, PRAS40 promoted AKT phosphorylation in Tsc2-depleted MEFs and mouse kidneys." (PMID 39333852, 2024). "Inhibition of mTOR by the addition of rapamycin, upregulation of TSC2 or blockade of STAT3 in monocytes/macrophages has been shown to promote the release of M1 cytokines and inhibit tumor growth, which was confirmed by reduced tumor angiogenesis." (PMID 39003350, 2024). "TSC2‐ EVs were found to enhance VEGF and HGF secretion from recipient fibroblasts, which we have previously shown to be a feature of a tumour‐supporting fibroblast phenotype." (PMID 37337371, 2023). "The lapatinib-treated tumor tissues showed reduced expression of p-mTOR, p-TSC2, and p-P70S6K in the TSC-NC and TSC2-WT groups." (PMID 37160904, 2023). "Mice receiving SA CAR-T cells displayed slower tumor growth for a longer duration as compared with mice receiving WT CAR-T cells and TSC2–/– CD70 CAR-T cells." (PMID 37788104, 2023). "TSC-related abnormalities such as tumour prevalence, location and size were analysed for each organ in addition to neuropsychiatric involvement and were compared between TSC1 and TSC2 mutant genotypes." (PMID 35440050, 2022). "We also examined tumor xenograft growth in FLCN-depleted, TSC2 KO cells stably expressing FLCNF118D or a combination of FLCNF118D/ FNIP2." (PMID 36357396, 2022). "In this study we evaluated the potential of multiparametric 1H magnetic resonance imaging (mpMRI) to monitor tumor response to therapy in a preclinical model of TSC, the transgenic mouse A/J Tsc2+/-." (PMID 35814396, 2022). "Unexpectedly, mTORC1 inhibition with rapamycin actually promoted TFEB phosphorylation in TSC2 KO cells and xenografts, restored TFEB cytosolic localization and potently inhibited TSC2 KO tumor xenograft growth." (PMID 36357396, 2022). "Overall, most patients with multiple CR had either two or three tumours, representing 43% and 65% of the patients in TSC1 and TSC2 cohorts, respectively." (PMID 35440050, 2022). "TSC1 contributes to both tumor-suppressive and pro-metastatic action of the TGF-β-Smad pathway and works independently of TSC2, which is essential for cellular growth arrest and epithelial to mesenchymal transition." (PMID 34229737, 2021). "Among others, PD-L1, ERG, Integrin-β5, Survivin, TGF-β, phosphorylated-TSC2 as well as partners of the MAP-kinase and mTOR pathways emerged as differentially expressed endpoints in tumor-derived EVs." (PMID 34155195, 2021). "SCID/Beige mice received 1 × 106 LB1 Tsc2–/– tumor cells expressing GD3 subcutaneously, and tumor development was visible in 10–15 days (~6 mm3)." (PMID 34806651, 2021). "In tumor cells, EZH2 epigenetically represses negative regulators of mTOR (e.g., TSC2 and RHOA), thus inhibiting tumor cell autophagy and accelerating tumorigenesis." (PMID 32999031, 2020). "The TSC1 and TSC2 genes are located at chromosomes 9q34 and 16p13.3, respectively, and according to Knudson’s tumor suppressor model, it has been established that TSC1 and TSC2 are involved in the development of TSC syndrome." (PMID 30842342, 2019).
tumor (continued). "TSC2 is a tumor suppressor that forms a complex with TSC1 and inactivation of the TSC1/TSC2 complex activates mTORC1 with its specific protein Raptor." (PMID 31244863, 2019). "Energy stress, through activation of AMPK is also upstream of TSC1/TSC2, where AMPK-dependent phosphorylation of TSC2 on Thr1227 and Ser1345 activates the TSC1/TSC2 tumour suppressor, leading to mTORC1 inhibition." (PMID 29547541, 2018). "Tuberous sclerosis complex 1 (TSC1), TSC2, and PTEN (phosphatase and tensin homolog) tumor suppressors are major negative regulators of mTOR signaling pathway." (PMID 29362480, 2018). "Intriguingly, some of these molecules are related to oncogenesis and tumour progression/metastasis, namely, HRAS, KRAS, TGFBR1, TGFBR2, RB1, ITGA6, ITGB4, mTOR, TSC2 and APLP2." (PMID 30258067, 2018). "To test the anti-tumour efficacy of GSK2126458, we first determined the maximum tolerated dose (MTD) of GSK2126458 in Tsc2+/- mice in a two weeks’ pilot study." (PMID 28938574, 2017). "The tumour suppressors, Tuberous Sclerosis Complex (TSC)-1 and TSC2, lie upstream of mTORC1 and function together with TBC1D7 to negatively regulate the mTORC1 activator, Ras homolog enriched in brain (Rheb)." (PMID 28415776, 2017). "However, it is not clear whether the reactivation was mediated through SGK3 phosphorylating TSC2 at Akt sites (Thr1462), since the tumour samples obtained from monotreated (MK‐2206) or combination (MK‐2206 and 14h) mice showed similar level of TSC2 phosphorylation." (PMID 27481935, 2016). "LAM has many similarities to a neoplastic disease: LAM cells are clonal, disseminating, and TSC-2 null cells have a metabolic signature suggesting an increased reliance on glycolysis and upon glutamine as a substrate." (PMID 25978616, 2015). "Previous data showed that inhibition of mTOR by rapamycin up-regulated PDGFR expression in Tsc1−/− and Tsc2−/− cells, and subsequently enhanced PI3K/AKT activation, which reversed the impaired tumor formation by Tsc1−/− and Tsc2−/− cell lines." (PMID 22428038, 2012). "We undertook a detailed examination of the phosphorylation of three well-characterised Akt substrates in the tumour samples: PRAS40 (on Thr246), TSC2 (on Ser939) and TBC1D4 (on Thr642)." (PMID 21505451, 2011). "In some tumours, phosphorylation of a substrate was observed to increase under conditions where the phosphorylation of Akt and one or both of PRAS40 and TSC2 were unchanged or decreased." (PMID 21505451, 2011). "In tumor-like cells, ERK phosphorylates TSC2 leading to the dissociation of TSC1/TSC2 complex with subsequent up-regulation of mTORC1." (PMID 21200439, 2010). "Two tumor suppressors gene products have been identified as the upstream activator and downstream effector of AMPK, namely LKB1 and TSC2, respectively." (PMID 17623090, 2007). "TSC2 functions as a tumor suppressor and is a critical negative regulator of the pro-oncogenic mTOR signaling pathway." (PMID 41522204, 2026). "Moreover, lncRNA ACTA2-AS recruits EZH2 to the TSC2 gene promoter, suppressing TSC2 expression, inhibiting autophagy, promoting apoptosis in cisplatin-resistant NSCLC cells, and limiting tumor progression." (PMID 40723840, 2025). "Additionally, both in vitro and in vivo experiments were undertaken to validate the tumor-suppressing capabilities of SERPING1 specifically and regulation of TSC2/mTOR pathway in LUAD." (PMID 39962118, 2025). "As expected, we detected positive enrichment of gRNAs targeting tumor suppressors, PTEN, TSC1, and TSC2, in both DMSO- and imlunestrant-treated cells on days 14 and 31, indicating that loss of PTEN and TSC1/2 enhance tumor cell growth without and with imlunestrant treatment." (PMID 40327396, 2025). "Amongst these are notable tumor related genes AKT3, CDKN1A, ESR1, FOXO1, TSC2, ERBB3, and NRG4." (PMID 40522948, 2025).
tumor (continued). "This distinction underscores the complexity of mTOR pathway regulation in UCS and indicates that TSC2 and PIK3CA may exert their effects on tumor biology via divergent mechanisms." (PMID 41181577, 2025). "This process is caused by the overexpression of HIF1-α, mediated by the mTOR pathway through the alteration of tumor suppressor genes, such as serine/threonine kinase 11 STK (STK11), TSC complex subunit 1 (TSC1), TSC complex subunit 2 (TSC2) and AKT serine/threonine kinase 1 (AKT1)." (PMID 37239099, 2023). "For Tsc2-intact tumors, there was a modest inhibition of tumor growth by anti–PD-1 antibody treatment, without statistical significance." (PMID 35119931, 2022). "TSC2 mRNA level was negatively correlated with the infiltration of CD8+ T cell, CD4+ T cell, regulatory T cell, dendritic cell, natural killer cell, and macrophage (tumor purity adjustment)." (PMID 35119931, 2022). "Deleterious mutations in the tumour suppressor genes, Tuberous Sclerosis Complex 1 (TSC1) and TSC2, were also identified which have not been previously reported to our knowledge." (PMID 35201535, 2022). "As FNIP1/2 and Tsc1, respectively, have established roles as guardians of these tumor suppressors, it follows that there may be a role for molecular chaperones in mediating FLCN and Tsc2 stability." (PMID 35883484, 2022). "An exponential graph of resolution of tumours over time revealed an average CR resolution age of 6.8 years old, with an average resolution age of 6.7 years old in TSC1 patients, and 7.2 years old in TSC2 patients." (PMID 35440050, 2022). "In murine kidney TsC2+/- tumors, metformin was able to reduce mTOR signaling only in normal tissues but not in tumor cells." (PMID 33821877, 2021). "Alterations in cell cycle regulatory genes were also detected in the tumor DNA of patients enrolled in the phase Ib BISCAY trial, in which 15% of patients with UC carried an amplification in RICTOR or a deleterious alteration in TSC1/TSC2." (PMID 34030643, 2021). "FOXA1, STK11, TSC1 and TSC2 were found to have no concordance between tumours and were largely restricted to metastases." (PMID 32811538, 2020). "The lung morphology observation showed that TSC2-null cell lesions in mice tended to accumulate around the veins and arteries [there were no other tumor lesions in other organs]." (PMID 32063747, 2020). "Another study observed fewer renal tumors in Tsc2+/− Beclin 1+/− mice than in Tsc2+/− mice and extensive central necrosis of xenograft tumors, indicating that downregulated autophagy level inhibited cell survival in TSC-related tumor." (PMID 33072782, 2020). "He underwent a biopsy of the dominant 6 cm retroperitoneal mass, from which DNA was isolated and subjected to paired tumor-germline next-generation sequencing via MSK-IMPACT, which confirmed the absence of a TSC2 germline mutation." (PMID 30285856, 2018). "Treatment of mice with AOD did not affect the initiation of TSC2-proficient tumors but had a substantial inhibitory effect on tumor growth (compare graphs a and b)." (PMID 29449538, 2018). "Generally speaking, TSC2 exerts its tumor suppressor function through negative regulation mTOR pathways which negatively regulate autophagy." (PMID 28387735, 2017). "Moreover, our Immunohistochemical staining assay with tumor samples further revealed a close correlation between BRSK2 protein level and TSC2 Ser1387 phosphorylation level." (PMID 28591720, 2017). "Four tumor samples showed copy number loss or a mutation of TSC1 and one tumor showed loss of TSC2; these events were evenly divided over responders and non-responders." (PMID 28903445, 2017). "Here we show that TSC2 knockdown transforms senescence-resistant cultured mouse and human renal epithelial cells into neoplastic stem cells that serially propagate renal AML-like tumours in mice." (PMID 29133867, 2017).
tumor (continued). "Given that other mice with mTORC1 repressor gene knockouts, such as TSC1 and TSC2, show these phenotypes at comparable embryonic stages, we extended our analysis to older animals, where TSC heterozygotes show increased tumour incidence in the kidney and at other sites." (PMID 28974734, 2017). "Constitutive activation of mTOR signalling by the deletion of the Lkb1/Tsc1/Tsc2 gene in both OSE and stromal cells causes OSE hyperplasia and epithelial OvCa but no stromal tumours." (PMID 27036037, 2016). "AMPK phosphorylation was impaired in our TSC2-/- hearts, conversely the level was reported to be increased in tumor-derived cells or neurons lacking TSC2." (PMID 27023784, 2016). "TSC1 and TSC2 form a membrane-bound tumor suppressor complex, in which TSC1 functions as the regulatory component stabilizing TSC2 and facilitating the catalytic activity of TSC2 as a GAP for the small GTPase Rheb, a positive regulator of mTORC1, cell growth and proliferation." (PMID 25360538, 2014). "The ERα gene signature was used to filter expression levels in tumor samples (either ERα-positive or ERα-negative) and the mTOR associated genes Rictor, Raptor, Rheb, TSC1, TSC2, and mTOR were analyzed." (PMID 25283550, 2014). "One major target of p-Akt is mTOR, which is activated through p-Akt-induced direct phosphorylation and inhibition of TSC2, a tumor suppressor protein that functions as a negative regulator of mTOR." (PMID 24228033, 2013). "Besides being directly activated by tumor-suppressor LKB1, AMPK itself regulates the activation of two other tumor suppressors, TSC1 and TSC2, which are critical regulators of Rheb and mTOR." (PMID 22353783, 2012). "A diet free of carbohydrate without caloric restriction was not effective in controlling TSC2-tumor growth, but changed the consistency of the tumors by inducing necrosis." (PMID 22018000, 2011). "In the Tsc2-/- subcutaneous tumor mouse model, vincristine is not effective, but angiogenesis inhibitors (sunitinib and bevacizumab) and asparaginase are effective as single agents." (PMID 20146790, 2010). "Since A/J Tsc2+/- mice have a higher average score per kidney at nine months of age than C57BL/6 Tsc2+/- mice at 12 months of age, these data show that the A/J Tsc2+/- strain has a significantly higher tumor burden than the C57BL/6 Tsc2+/- strain." (PMID 20146790, 2010). "Tumor cells showed overexpression of cyclin D1 but lacked the loss of heterozygosity of the TSC1 and TSC2 genes." (PMID 19265534, 2009). "Microscopic assessment of the ENU-treated Tsc2+- mice confirmed this enhancement in tumor development (data not shown)." (PMID 19527517, 2009). "Since NVP-BEZ235 had effects in inhibiting mTOR, and at low doses could reduce tumor development in this model, we treated a cohort of ENU-treated Tsc2+- mice with NVP-BEZ235 at full dosage, 45 mg/kg PO QD, and compared outcome with RAD001 treatment." (PMID 19527517, 2009). "Similarly, KMT2B and TSC2 mutations, although not well‐studied in CRC, have been implicated in other malignancies for their roles in enhancing tumour aggression and stemness, further supporting their inclusion as high‐risk markers in our model." (PMID 39777996, 2025). "Because Tsc1 − / − or Tsc2 − / − MEFs have low tumorigenic ability in vivo, we constructed a novel cell line (NTC/T1 null cells) with potent tumorigenicity derived from a subcutaneous tumor formed by the injection of Tsc1 − / − MEFs into nude mice to investigate the in vivo role of ERO1α." (PMID 38610018, 2024). "Radiological investigations confirmed the site of the tumor, and a positive expression of thyroid transcription factor 1 in the ganglion cell component, along with the absence of germline mutation in TSC1 and TSC2, led to the final diagnosis of SEGA without TSC." (PMID 39130912, 2024).
tumor (continued). "The promotion of the cell cycle pathway and inhibition of TSC tumor suppressor by ERCC GSVA indicated the potential biological function of this gene family beyond base excision repair or regulation of the expression and function of these genes like TSC1 or TSC2." (PMID 39582530, 2024). "Next, we further determined whether the ablation of Tsc2 alone could also accelerate c-MYC tumor development without MCL1." (PMID 39325536, 2024). "However, no further tumour regression was observed in either TSC1 or TSC2 patients beyond 15.5 years of age, meaning that for approximately 16% of patients, CR persisted into adulthood." (PMID 35440050, 2022). "Besides, flow cytometry showed that depletion of Tsc2 in KP cells did not increase the tumor antigen expression (Ova) or presentation via major histocompatibility complex molecules (H-2) in the coculture system." (PMID 35119931, 2022). "A combination of rapamycin and resveratrol tested in an animal model was able to specifically inhibit the PI3K/Akt/mTORC1 signaling pathway, activating apoptosis and reducing cell survival in a TSC2-/- xenograft tumor model of LAM but not in cells expressing TSC2." (PMID 33821877, 2021). "Additionally, tumor cells' characteristics such as receptors (insulin/IGF1) and pathway proteins (PI3K/mTOR, LKB1, and TSC2) expression might potentially mediate these indirect, host-mediated effects and any direct effects that are extremely important." (PMID 33531904, 2021). "The products of TSC1 and TSC2 gene form a functional complex with GTP enzyme activating protein (GAP) activity, which has the effect of inhibiting the target of mammalian rapamycin complex 1 (mTORC1), while mTORC1 is constitutively activated in TSC mutant tumor." (PMID 32532965, 2020). "Given the absence of a second TSC2 variant, TSC2-LOH or any other evident tumor driver apart from the unclear variant in SIPA1L3 in the renal and hepatic AMLs of the herewith reported individual, a contribution of the germline ARID1B variant to the tumorigenesis cannot be excluded." (PMID 31077186, 2019). "However, TSC2 mutations have not been identified in all cases of LAM, possibly due to technical limitations related to the small amount of tumor tissue available." (PMID 27494029, 2016). "Nonetheless, the Tsc2-driven tumour development might not reflect the sporadic pathogenesis of myomas." (PMID 27716434, 2016). "Concordant with these mutation findings in TSC2, TSC2 LOH was also seen in 5 AMLs; tumor impurity may have contributed to the lack of TSC2 LOH in the other 4 cases." (PMID 21949787, 2011). "Indeed, if the tumour suppressor genes were inactivated, the absence of the TSC2 protein would be expected and this was not the case." (PMID 19401700, 2009). "By acting on the TSC complex subunit 1 (TSC1)/TSC2 complex and the mechanistic target of rapamycin complex (mTOR) signal transduction, AKT might mediate a variety of cellular functions, including cell proliferation, differentiation, invasion, tumor angiogenesis, and metastasis 65-68." (PMID 36605482, 2023). "We also found that angiogenesis inhibitors and asparaginase reduce tumor growth in a TSC2 tumor mouse model and although these drugs are not as effective as rapamycin, these drug classes may have some therapeutic potential in the treatment of TSC related tumors." (PMID 20146790, 2010). "The proportion of individuals with multiple CRs as opposed to an isolated tumour stands at 86% of TSC1 patients and 89% of TSC2 patients with cardiac manifestations." (PMID 35440050, 2022). "These new co-chaperones mediate the stability of critical tumor suppressors FLCN and Tsc2 as well as the various classes of Hsp90 kinase and non-kinase clients." (PMID 35883484, 2022).